SCNN1G (sodium channel epithelial 1 subunit gamma)
Description:
This is one of the three pore-forming subunits of the heterotrimeric epithelial sodium channel (ENaC), a critical regulator of sodium balance and fluid homeostasis. ENaC operates in epithelial tissues, where it mediates the electrodiffusion of sodium ions from extracellular fluid through the apical membrane of cells, with water following osmotically. It plays a key role in maintaining sodium homeostasis through electrogenic sodium reabsorption in the kidneys. Additionally, ENaC is essential for airway surface liquid homeostasis, which is crucial for proper mucus clearance.
Synonyms: ENaCG; ENaCgamma; SCNEG; BESC3; LDLS2; PHA1; PHA1B3
Tractability: Small molecule: an approved drug acts on it; it belongs to a druggable protein family. Antibody: UniProt places it where antibodies can reach, with high confidence; its Gene Ontology location is reachable by antibodies, with high confidence; UniProt predicts a signal peptide or a membrane-spanning region. PROTAC: UniProt records ubiquitination sites on it.
Target class: Ion channel; Ligand-gated ion channel; Epithelial sodium channel
Chemical probes: BI-8668 (high quality)
Gene: Protein-coding gene on chromosome 16 (23,182,677 to 23,216,883, forward strand). Ensembl gene ENSG00000166828.
Subcellular location: Apical cell membrane
Subcellular location (Human Protein Atlas): Plasma membrane; Nucleoplasm; Primary cilium; Primary cilium transition zone
Pathways (Reactome):
Sensory Perception: Sensory perception of salty taste
Transport of small molecules: Stimuli-sensing channels
Gene Ontology:
Molecular function: monoatomic ion channel activity; protein binding; sodium channel activity; WW domain binding; ligand-gated sodium channel activity; sodium ion transmembrane transporter activity
Biological process: cellular response to acidic pH; intracellular sodium ion homeostasis; multicellular organismal-level water homeostasis; sodium ion homeostasis; sodium ion import across plasma membrane; sodium ion transmembrane transport; cellular response to aldosterone; cellular response to vasopressin; regulation of blood pressure; sensory perception of salty taste; sensory perception of sour taste; sodium ion transport
Cellular component: apical plasma membrane; extracellular exosome; plasma membrane; sodium channel complex; external side of plasma membrane; membrane
Genetic constraint (gnomAD): Loss-of-function variants: 25 observed, 65.76 expected, observed/expected ratio (o/e) 0.38, 90% interval 0.28 to 0.53. The upper end of that interval is the gene's LOEUF score, 0.53, which puts it in group 2 of 6, group 1 being the genes least tolerant of losing a copy. Missense variants: 732 observed, 849.04 expected, observed/expected ratio (o/e) 0.86, 90% interval 0.81 to 0.92. Synonymous variants: 326 observed, 327.83 expected, observed/expected ratio (o/e) 0.99, 90% interval 0.91 to 1.09.
Gene-disease validity (ClinGen):
ClinGen rates the evidence that SCNN1G causes each of these diseases.
Liddle syndrome (autosomal dominant): Definitive. A rare genetic form of low-renin hypertension characterized by hypertension associated with decreased plasma levels of potassium and aldosterone.
Homologues: Orthologues: chimpanzee SCNN1G (99% identical), macaque SCNN1G (98% identical), dog SCNN1G (89% identical), pig SCNN1G (88% identical), rat Scnn1g (86% identical), mouse Scnn1g (86% identical), guinea pig SCNN1G (84% identical), rabbit SCNN1G (76% identical), tropical clawed frog scnn1g (58% identical), Caenorhabditis elegans mec-10 (22% identical), Caenorhabditis elegans mec-4 (21% identical), Caenorhabditis elegans acd-2 (18% identical), and 21 more. Paralogues in human: SCNN1B (36% identical), SCNN1A (32% identical), SCNN1D (26% identical), ASIC5 (20% identical), ASIC1 (19% identical), ASIC3 (19% identical), ASIC2 (18% identical), ASIC4 (17% identical).
Diseases named in the same sentence as SCNN1G in open-access papers:
SCNN1G is named in the same sentence as 52 diseases in open-access papers, as found by Europe PMC text mining. Sharing a sentence is not in itself a finding about the gene and the disease. The quoted sentences say what the papers report.
Hypertension (9 papers, 2009 to 2022). The presence of chronic increased pressure in the systemic arterial system. "Epithelial sodium channels (ENaC), are the main regulators for sodium transport in the kidney, and rare variants in SCNN1G cause Liddle Syndrome, a monogenic form of hypertension." (PMID 24658007, 2014). "Mutations in the gene encoding the γ-subunit of ENaC, SCNN1G, were identified as causes of Mendelian forms of hypertension and hypotension." (PMID 25157616, 2014). "Constitutive activation variants of SCNN1B or SCNN1G result in salt-sensitive hypertension known as Liddle’s syndrome, an autosomal dominant form of monogenic hypertension that is characterized by early-onset of low-renin hypertension." (PMID 30832344, 2019). "Liddle syndrome is genetic autosomal dominant form of low renin arterial hypertension caused by germline mutations in the SCNN1A, SCNN1B and SCNN1G genes, encoding, respectively, the α, β and γ subunits of the epithelial sodium channel ENaC." (PMID 29534496, 2018). "Liddle syndrome is an autosomal dominant genetic condition that causes hypertension and hypokalemia due to a gain-of-function mutation in the SCNN1B or SCNN1G genes which code for the epithelial sodium channel in the kidney." (PMID 28396810, 2017).
Liddle syndrome (8 papers, 2014 to 2023). "Here, we describe a Russian family suffering from the Liddle syndrome due to frameshift mutation in the SCNN1G gene." (PMID 31655555, 2019). "The cause of Liddle syndrome is missense or frameshift mutations in SCNN1A, SCNN1B, or SCNN1G genes that encode epithelial sodium channel subunits." (PMID 31655555, 2019). "Liddle syndrome is associated with germline mutations in an allele of SCNN1A, SCNN1B or SCNN1G genes." (PMID 31655555, 2019). "The molecular basis of Liddle syndrome resides in germline mutations of the SCNN1A, SCNN1B and SCNN1G genes, encoding the α, β, and γ-subunits of the epithelial Na+ channel (ENaC), respectively." (PMID 29534496, 2018). "Genetic analysis revealed that Liddle syndrome was due to mutations in ENaC subunits, mainly ENaCβ and γ (SCNN1B and SCNN1G genes), leading to the modifications (generally truncation) of a prolin‐rich sequence called PY motif, in the C‐terminal part of the protein." (PMID 35909256, 2023). "Liddle syndrome results from germline mutations in SCNN1A, SCNN1B or SCNN1G genes." (PMID 29534496, 2018). "Furthermore, some genes may be completely lacking in the zebrafish, such as the ENaC (epithelial Na channel) subunits (SCNN1A, SCNN1B, SCNN1G, and SCNN1D), mutations in which cause Liddle syndrome and pseudohypoaldosteronism type 1 in humans." (PMID 30200518, 2018). "The diagnosis of Liddle syndrome is based on SCNN1A, SCNN1B and SCNN1G gene sequencing." (PMID 29534496, 2018).
bronchiectasis (5 papers, 2008 to 2025). Segmental, irreversible dilation of the bronchial tree resulting in the accumulation of secretions which leads to obstruction. "In addition, SAE ionocytes also expressed the high levels of epithelial Na+ channel genes (SCNN1A, SCNN1B, SCNN1G), risk genes relevant to CF and bronchiectasis." (PMID 32727470, 2020).
pseudohypoaldosteronism type 1 (2 papers, 2014 to 2018). A rare, primary form of mineralocorticoid resistance characterized by mild to profound salt wasting either restricted to the kidney (renal pseudohypoaldosteronism type 1), or generalized affecting many organs (generalized pseudohypoaldosteronism type 1). "Other variants in SCNN1G cause pseudohypoaldosteronism type 1, a rare inherited form of renal tubular acidosis." (PMID 24658007, 2014).
asthma (1 paper, 2026). "In ex vivo severe asthma bronchial biopsies, the protein levels were upregulated 1.2-fold for PHLDB2 (p = 0.2844), 2.4-fold (p < 0.01) for NEK6, and 2.0-fold for SCNN1G (p < 0.05)." (PMID 41664127, 2026).
autosomal recessive PHA-1 (1 paper, 2023). "The second type of PHA-1 is the generalized, systemic PHA-1 form, also called autosomal recessive PHA-1 (or PHA-1B), caused by loss-of-function mutations in the SCNN1A, SCNN1B, and SCNN1G, genes which encode α-, β- and γ-ENaC subunits, respectively." (PMID 37175488, 2023).
cervical cancer (1 paper, 2022). A primary or metastatic malignant neoplasm involving the cervix. "In addition, SCNN1G is downregulated in cervical cancer and is negatively correlated with the histological grade of the tumor, and its overexpression is associated with better OS." (PMID 36389709, 2022).
head and neck squamous cell carcinoma (1 paper, 2023). A squamous cell carcinoma that arises from any of the following anatomic sites: lip and oral cavity, nasal cavity, paranasal sinuses, pharynx, larynx, and salivary glands. "In addition, the SCNN1G gene coding for the γ subunit of ENaC has been studied in head and neck squamous cell carcinoma, where it is downregulated, and this correlates with tumor metastasis and poor prognosis in HNSCC patients, suggesting a tumor suppressor role." (PMID 37408210, 2023).
metastatic melanoma (1 paper, 2021). A melanoma that has spread from its primary site to another anatomic site. "Even more decrease of the ACCN3, SCNN1A, and SCNN1G expression was observed in comparison of primary malignancies and metastatic melanoma samples." (PMID 34680442, 2021).
pseudohypoaldosteronism (1 paper, 2016). An inherited or acquired disorder of electrolyte metabolism, characterized by the inability of the renal tubules to respond to aldosterone. "One girl showed pseudohypoaldosteronism related to mutations of the SCNN1G gene encoding for the epithelial sodium channel." (PMID 27485500, 2016).
tumor (5 papers, 2009 to 2023). "The findings revealed that ANO1, AQP9, and BEST2 were upregulated in tumor tissues, and AQP5, SCN4A, and SCNN1G expression was upregulated in normal tissue from 12 HNSCC patients." (PMID 36389709, 2022). "In the TCGA-HNSC cohort, we observed the expression of 12 ion channel genes in tumor and normal tissues; ANO1, AQP9, BEST2, CHRNA5, and KCNJ15 were upregulated in HNSCC, while AQP1, AQP5, SCNN1G, and SCN4A were downregulated." (PMID 36389709, 2022).
Respiratory disease (1 paper, 2013). "Respiratory disease biomarkers like ARG2, SCNN1G, EPB41L4B, CSF1, PTEN, TUBB1, and ESR2 were also detected." (PMID 24382964, 2013).
SCNN1G also shares sentences with these, for which no sentence is quoted: cancer (4 papers); Hyponatremia (4); Ewing sarcoma (2); fibromatosis (2); Hyperkalemia (2); respiratory infections (2); ulcerative colitis (2); Ureteral obstruction (2); adenocarcinoma (1); adrenogenital syndrome (1); Arrhythmia (1); bladder cancer (1); breast carcinoma (1); cervical adenocarcinoma (1); cholelithiasis (1); Crohn disease (1); cystic fibrosis (1); gastric cancer (1); genetic disorder (1); gynecological cancers (1); head and neck cancer (1); Hypernatremia (1); Hypokalemia (1); idiopathic bronchiectasis (1); infection (1); keloid (1); lung adenocarcinoma (1); melanoma (1); metabolic (1); miliaria rubra (1).
A further 10 diseases each share a sentence with SCNN1G in 1 paper.